ENSG00000207410
Synonyms: LOC124900398
Gene: Small nucleolar RNA gene on chromosome 17 (67,271,469 to 67,271,607, forward strand). Ensembl gene ENSG00000207410.
Gene Ontology:
Biological process: RNA processing
Cellular component: nucleolus
Homologues: Orthologues: mouse Gm25791 (86% identical), mouse Gm26236 (84% identical). Paralogues in human: SNORA8 (94% identical).